ATM (ATM serine/threonine kinase)
Diseases named in the same sentence as ATM in open-access papers (continued):
Sharing a sentence is not in itself a finding about the gene and the disease.
tumor (continued). "Indeed, targeting members of DDR such as ATM (ataxia telangiectasia mutated) and CHK1 (checkpoint kinase 1), amplifies DNA damage and induces lethality on tumor cells." (PMID 31947935, 2020). "Indeed, the delivery of smaller concentrations of both ATM and DNApk-cs siRNA resulted in the greatest inhibition of DNA damage repair and radiosensitization for all tumor cell lines tested." (PMID 33158243, 2020). "This leads to the question of how to identify ATM-null tumours in a clinical setting." (PMID 32741974, 2020). "Thus, ATM-ATR-Chk1-dependent DNA damage signaling within damaged tumor cells is involved in regulating PD-L1 expression in response to DNA damage." (PMID 33102516, 2020). "In summary, we identified for the first time that the co-expression of F and HN and oncolytic NDV infection activated the ATM-mediated DSB signaling pathway in tumor cells via the ATM-Chk2 axis, which then promoted syncytium formation and facilitated NDV replication." (PMID 32479542, 2020). "In our present cohort we observed 11% (6/53) of patients harboring ATM alterations in the tumor." (PMID 33098265, 2020). "We therefore speculate that continued intermittent combination treatment of the FaDu ATM-KO xenograft may also induce tumour regression beyond the synergistic growth inhibition observed in the study-period tested." (PMID 32444694, 2020). "In further clinical research, combinations of photons or chemotherapy drugs with the ATM inhibitor AZD0156 may achieve a better effect in repressing tumor growth for advanced BTC patients with low DNA polymerase θ expression." (PMID 33182492, 2020). "Therefore, the proposed mechanism behind the synthetic lethal relationship between ATR and ATM is that ATR inhibition increases the number of DSBs and tumor-specific loss-of-function mutations in ATM impair the repair of these DSBs." (PMID 32731592, 2020). "Very recently, molecular insights have emerged about the role of FANCS (BRCA1) in regulating the mitophagy process; FANCS, indeed, inhibits ataxia-telangiectasia mutated (ATM)-AMP-activated protein kinase (AMPK)-DRP1-mediated mitochondrial fission and promotes tumor proliferation and invasion." (PMID 32962238, 2020). "In relation to ATRi/gem in PDAC, our data would support the use of complete ATM loss (i.e. 0% ATM tumour cell nuclear staining), as opposed to <10 or 25% staining, since only ATM-null cells appeared to be hypersensitive." (PMID 32741974, 2020). "Finally, Singhi and colleagues performed targeted genomic profiling in 3594 tumor samples from unselected patients with PDAC and found pathogenic germline ATM variants in 48 patients (1.3%)." (PMID 31963441, 2020). "We also detected the level of ATM/ATR-mediated SerRS phosphorylation in tumor tissues." (PMID 33351793, 2020). "miR-421 and miR-101 suppress ATM expression and sensitize tumor cells to radiation." (PMID 33317198, 2020). "Finally, several miRs are related to tumor radioresistance management, where, thanks to the inhibition of ATM protein, they can modulate DNA damage response sensitizing tumor cells to radiotherapy." (PMID 32793185, 2020). "Note that treatment using an intermittent ‘5 day on’ schedule in the FaDu ATM-KO model was stopped after 21 days due to tumour ulcerations, compared with 130-day treatment in the CTG-0828 model, and that tumour regressions of the CTG-0828 PDX were only detected after 20 days." (PMID 32444694, 2020).
tumor (continued). "Interestingly, no synergistic effect was observed with the combination of HITT overexpression and ATMi-1, which further supports the idea that HITT inhibits tumor growth by preventing the activation of ATM." (PMID 32203529, 2020). "Inactivating mutations including any in the ATM/Chk2 or ATR/Chk1 pathways potentially would remove the barrier to progression and result in cell proliferation and survival, increasing genomic instability and tumor progression." (PMID 32566745, 2020). "One important gene involved in both rare genetic and neoplastic diseases is the ATM gene." (PMID 32127026, 2020). "Therapeutic targeting of metabolic pathways that function independent of DDR to support tumor survival represents an attractive strategy for improving treatment efficiency in ATM deficient lymphoid malignancies." (PMID 33273545, 2020). "In this work we have studied the effect that VRK1 depletion has on the cellular response to olaparib, a drug which is currently used to sensitize tumor cell to ionizing radiation, and facilitates tumor elimination in cells with altered DNA repair pathways, such as those with BRCA1 or ATM mutations." (PMID 31101118, 2019). "We speculate that even low levels of ATM expression may confer resistance to PARP inhibition, and further investigation to determine whether tumours with low or mutated ATM will be sensitive to olaparib plus or minus an ATR inhibitor." (PMID 31481733, 2019). "This pathway was enriched for functional mutations in three of the five patients with residual disease, although sample size limits insight into whether ATM signalling alterations differentiate responders from resistant tumours." (PMID 30763338, 2019). "Limitations of our study are the small sample size, the focus on BRCA2 and ATM mutations, the lack of tumor mutational burden measurements, and that no MDSCs were analyzed." (PMID 31549213, 2019). "DNA damage-induced tumour cell killing has been demonstrated in preclinical models with mirin and KU-60019 and other ATM inhibitors are currently in trials that potentially could be re-purposed for SCI." (PMID 32954257, 2019). "In tumour cells lacking DNA-PKcs, and in rodent and human cells treated with siRNA to DNA-PKcs,50–52 loss of DNA-PKcs resulted in an ~80% reduction in ATM protein expression." (PMID 31481733, 2019). "The increase in micronuclei formation and the chromosomal aberration profile we observed following combination treatment suggested that we are achieving an additive efficacy of the two agents in ATM KO cells in vitro, which translates to profound tumour regressions in vivo." (PMID 31699977, 2019). "In addition, we observed reduced ATM staining level in tumor tissues obtained from CP466722-treated A549cisR-incoulated mice compared to the vehicle-injected A549cisR-incoulated mice." (PMID 30961670, 2019). "Notably, treatment of 22Rv1 tumor-bearing mice with ENZ alone activated ATM (pATM) in vivo, as it did in vitro, but as expected did not cause cell death (TUNEL assay)." (PMID 31083651, 2019).
tumor (continued). "Overexpression of both MRE11 and ATM was also related to lymph node positivity, suggesting that the observed poor overall survival was likely due to aggressiveness and metastatic properties of the tumour cells." (PMID 30769804, 2019). "A total of 696 tumours were suitable for ATM and MYC protein expression analyses." (PMID 30746633, 2019). "Furthermore, p-rpS6, p-e-IF4E, p-ATM, and p-DNA-PKcs expression was significantly attenuated in tumor cells after RT + BEZ235 + mBEZ235 treatment when compared with those after RT + BEZ235 treatment." (PMID 31430901, 2019). "Morphology of ATM-associated tumours was compared with that of 599 patients with no BRCA1 and BRCA2 mutations from a hospital-based series, as well as with data from The Cancer Genome Atlas." (PMID 29665859, 2018). "This analysis did not allow separation of ATM-associated tumours according to molecular subtype, LOH status at 11q22 (ATM locus), type of inherited variant (TV vs. MS) or origin of HetAT participants (A-T families or HBOC families)." (PMID 29665859, 2018). "The specific HRR mutations identified in the 21 tumour samples were: BRIP1 (n = 5), CDK12 (n = 3), RAD54L (n = 2), RAD51B (n = 2), RAD54L rearr (n = 1), ATM rearr (n = 1), FANCA rearr (n = 1), FANCD2 (n = 1), FANCL rearr (n = 1), FANCL (n = 1), RAD51C (n = 1), RAD52 del (n = 1), XRCC3 rearr (n = 1)." (PMID 30353044, 2018). "Moreover, tumor cells can utilize two distinct kinase signaling cascades for the DNA damage repair here, including ATM-Chk2 and ATR-Chk1 axes." (PMID 29688867, 2018). "Moreover, ATM-activated Akt, a pro-survival signal, whose inhibition further enhanced (S)-crizotinib-induced inhibition of GC cell growth and tumor growth in xenograft mice, and re-sensitized resistant GC cells to (S)-crizotinib." (PMID 29855474, 2018). "In the present study, we report mutations in known tumor suppressor genes such as SMARCB1 and ATM." (PMID 30093964, 2018). "The absence of histological resemblance between BRCA1- and ATM-associated tumours was reflected at the molecular level." (PMID 29665859, 2018). "Indeed, an unexpected tumorigenic role for ATM, in particular, tumor contexts has been demonstrated." (PMID 29616191, 2018). "Targeting ATM might suppress tumor angiogenesis and enhance the effect of antitumor ROS-producing therapies." (PMID 29770165, 2018). "In human tumor tissues, elevated levels of activated ATM correlate with poor patient survival." (PMID 28337983, 2017). "Furthermore, a simple measure of ATM protein expression by IHC cannot establish the functional capability of ATM within the tumour." (PMID 28418844, 2017). "In addition, while genetic and pharmacologic inhibition of ATM markedly suppressed GBM tumor growth and promoted animal survival, restoring ATM levels in GBM cells ectopically expressing miR-203a increased tumorigenicity and decreased animal survival." (PMID 29348882, 2017). "Since miR-203a is a tumor suppressor in GBM we hypothesized that ATM has pro-tumorigenic activity in GBM." (PMID 29348882, 2017). "According to the results, decreased the expression of ATM is linked with angiogenesis and HIF-1α expression in HNSCC cells, suggestion that specific inhibitor regulating ATM pathway would be beneficial for suppressing tumor angiogenesis." (PMID 28881600, 2017).
tumor (continued). "Tissue microarrays, containing 165 formalin-fixed, paraffin-embedded resected NSCLC tumours from patients diagnosed at the Tom Baker Cancer Centre, Calgary, Canada, between 2003 and 2006, were analyzed for ATM expression using quantitative fluorescence immunohistochemistry." (PMID 28418844, 2017). "ATM could be a pivotal tumor suppressor in response to the translocation occurrence characteristic of eBL tumor cells." (PMID 29132323, 2017). "ATM and DNA-PK inhibitors dose dependently sensitized tumor cells for both radiation qualities." (PMID 29287602, 2017). "So, we could speculate that ATM could act as a ROS sensor modulating the autophagic flux according to ROS levels in different populations of cells within the tumor." (PMID 28423511, 2017). "Hence, tumor cells harboring disrupted components of this signaling pathway, such as low levels of ATM, display a paradoxically elevated mTORC1 activity in hypoxic tumor regions." (PMID 28280521, 2017). "Previous researches showed RSV triggered DNA damage and directly activated ATM in some tumor cells, but the effect of RSV in NKTCL is unknown." (PMID 28950914, 2017). "Thus, our study conclusively establishes that ATM’s main tumor suppressor role in the pancreas is to maintain genomic stability." (PMID 28894253, 2017). "To further investigate the role of ATM in tumor response, we then examined a separate institutional database of patients who underwent targeted sequencing analysis and identified eight patients with similar ATM mutations that received palliative RT, all of whom appeared to have excellent responses." (PMID 28055970, 2017). "It is tempting to speculate that HR or ATM signalling would have a tumour suppressor function after ADT and that down-regulation of HR is a mechanism whereby the tumour increases its ability to survive treatment." (PMID 28851861, 2017). "Blockage of ATM production totally reversed CUR suppressed angiogenesis in the xenografted tumor." (PMID 28881600, 2017). "Blockage of ATM production totally reversed CUR induced cell apoptosis in the xenografted tumor." (PMID 28881600, 2017). "Here, we demonstrate that approximately 20% of NSCLC cases show a reduced ATM expression in the malignant compared to the non-malignant components of the tumour and that this loss of ATM expression is associated with a worse prognosis." (PMID 28418844, 2017). "Olaparib treatment also sensitized ATM-null tumor cells to DNA-damaging agents." (PMID 29262669, 2017). "To determine if the tumor regression caused by combination treatment was associated with a DSB repair response, we assessed the expression of the DSB repair pathway-related proteins, ATM, DNA-PKcs and KAP1." (PMID 29348875, 2017). "Notably, the DDR pathway, through its upstream kinase ATM, also keeps in check another major tumor suppressor factor, namely p14ARF that functions as a second anti-tumor barrier to DDR activation." (PMID 28289428, 2017). "Other researchers previously reported that Hsp90 inhibitor DMAG impairs the radiation-induced activation of ATM in tumor-derived cell lines MiaPaCa, NCI-H460, and A549, which resulted in interfering with the post-radiation DNA repair and radiosensitizing the DMAG-treated cells." (PMID 28291803, 2017). "The ATM-EI was defined as the expression of ATM within the malignant cells of the tumour relative to the ATM expression in the adjacent tumour-associated non-malignant stromal cells." (PMID 28418844, 2017). "Using the ratio of ATM expression in the malignant component compared to the stromal elements of the tumor (the ATM-EI), we defined a cohort of 22% of patients whose NSCLC tumors could be described as being ATM-deficient." (PMID 28418844, 2017).
tumor (continued). "We also demonstrate the activation of the ATM pathway in the A antigen-expressing tumor cells." (PMID 28122343, 2017). "As another example, ctDNA analysis in BR28 showed that EGFR p.R521K and PTCH1 p.T1195S variants were more frequent than ATM pH1380Y, BRCA2 p.N289H, and BRCA2 p.N991D, whereas all these variants were present at a similar frequency in tumor tissue samples at diagnosis and after the 1st NAC cycle." (PMID 29156805, 2017). "Both ATR and DNA-PKcs expression was higher than ATM in all tumour classifications." (PMID 27527858, 2016). "ATM protein expression was analyzed in 259 central and 260 peripheral tumor cores." (PMID 27930716, 2016). "As expected, tumours grew at comparable speed indicating that the loss of ATM does not impact proliferation or survival on its own." (PMID 27922010, 2016). "Moreover, low ATM is strongly related to known poor prognostic factors such as larger tumor size, positive lymph nodes (LN), and high grade in ES-HPBC." (PMID 27741524, 2016). "Determining whether non-replicating cells are equally sensitized to ETs by dual inhibition of ATR and ATM than actively replicating tumor cells might be part of the answer." (PMID 27029031, 2016). "The MRE11/ATM two-protein panel developed in this study may have clinical value as a predictive marker of tumor response to neoadjuvant radiotherapy, and a prognostic marker for disease-free and overall survival." (PMID 27930716, 2016). "The data describing opposing roles of ATM and MAPK7 in cell cycle regulation and tumor growth suggest that these could be functionally linked." (PMID 27793024, 2016). "Thus, our experiments reveal an unexpected link between growth factor signalling pathways and ATM loss, providing a strong rationale for testing MEK inhibitors in the context of ATM mutant tumours." (PMID 27922010, 2016). "We hypothesized that acquired deficiencies in ATM and/or MRE11 would lead to a dysfunctional repair mechanism and an inability to restore genomic stability, resulting in increased tumor cell death following radiotherapy." (PMID 27930716, 2016). "Importantly, pimasertib treatment also resulted in a significant survival benefit for mice carrying ATM knockdown tumours." (PMID 27922010, 2016). "Although speculative, this list could include other key HDR genes including ATM, BRCA1/2, MRE11, RAD50, NBS1 or RAD51, which are also mutated in CRC and many other tumor types." (PMID 26318585, 2015). "Altogether, four pathways (Mitotic Roles of Polo-Like Kinase; ATM Signaling; Cell Cycle: G2/M DNA Damage Checkpoint Regulation; and Estrogen-Mediated S-Phase Entry) were the same as from the human array results which indicate the response from the tumor side." (PMID 26381735, 2015). "Hence, there is still controversial about the role of ATM, to suppress or activate tumor progression." (PMID 26528698, 2015). "Both DNAPK and ATM have been reported to regulate radiation survival of tumor cells." (PMID 26460618, 2015). "Together these data might rationalize why disabling ATM alterations are a selected genomic aberration in human neoplastic disease." (PMID 26113859, 2015).